ATP6V1E2 (ATPase H+ transporting V1 subunit E2)
Description:
Subunit of the V1 complex of vacuolar(H+)-ATPase (V-ATPase), a multisubunit enzyme composed of a peripheral complex (V1) that hydrolyzes ATP and a membrane integral complex (V0) that translocates protons. V-ATPase is responsible for acidifying and maintaining the pH of intracellular compartments and in some cell types, is targeted to the plasma membrane, where it is responsible for acidifying the extracellular environment.
Synonyms: ATP6E1; ATP6EL2; ATP6V1EL2; MGC9341; VMA4
Tractability: PROTAC: ubiquitination databases record sites on it.
Gene: Protein-coding gene on chromosome 2 (46,490,750 to 46,543,287, reverse strand). Ensembl gene ENSG00000250565.
Pathways (Reactome):
Transport of small molecules: Ion channel transport; Transferrin endocytosis and recycling
Cellular responses to stimuli: Amino acids regulate mTORC1
Immune System: ROS and RNS production in phagocytes
Signal Transduction: Insulin receptor recycling
Gene Ontology:
Molecular function: protein binding; proton-transporting ATPase activity, rotational mechanism
Biological process: proton transmembrane transport; regulation of macroautophagy
Cellular component: cytosol; acrosomal vesicle; proton-transporting two-sector ATPase complex, catalytic domain
Genetic constraint (gnomAD): Loss-of-function variants: 7 observed, 4.58 expected, observed/expected ratio (o/e) 1.53, 90% interval 0.8 to 1.93. That is too few expected variants to judge how well the gene tolerates losing a copy. Missense variants: 308 observed, 287.45 expected, observed/expected ratio (o/e) 1.07, 90% interval 0.98 to 1.18. Synonymous variants: 121 observed, 110.98 expected, observed/expected ratio (o/e) 1.09, 90% interval 0.94 to 1.27.
Homologues: Orthologues: chimpanzee ATP6V1E2 (99% identical), macaque ATP6V1E2 (97% identical), dog ATP6V1E2 (88% identical), pig ATP6V1E2 (87% identical), guinea pig ATP6V1E2 (85% identical), mouse Atp6v1e2 (79% identical), rat Atp6v1e2 (77% identical), rabbit ATP6V1E2 (77% identical), tropical clawed frog atp6v1e1 (73% identical), zebrafish atp6v1e1a (67% identical), zebrafish atp6v1e1b (67% identical), Drosophila melanogaster Vha26 (61% identical), and 1 more. Paralogues in human: ATP6V1E1 (77% identical).
Diseases named in the same sentence as ATP6V1E2 in open-access papers:
ATP6V1E2 is named in the same sentence as 16 diseases in open-access papers, as found by Europe PMC text mining. Sharing a sentence is not in itself a finding about the gene and the disease. The quoted sentences say what the papers report.
asthma (1 paper, 2024). "Single gene GSEA analysis revealed that HORMAD2, WNT10A, ATP6V1E2, CMBL, ARRDC4, and LPIN2 were primarily involved in Allograft rejection, Arginine biosynthesis, Asthma, and Fatty acid biosynthesis." (PMID 40635857, 2024).
infection (1 paper, 2013). The state of being infected such as from the introduction of a foreign agent such as serum, vaccine, antigenic substance or organism. "Western blot analyses revealed that the levels of VO subunits ATP6V0A1, ATP6V0A2, ATP6V0A3, and ATP6V0C were significantly decreased in the floxed MEFs after Ad-Cre infection, but V1 subunit ATP6V1E2 was unaffected." (PMID 24223829, 2013).
ATP6V1E2 also shares sentences with these, for which no sentence is quoted: cancer (2 papers); tumor (2); adult-onset Still disease (1); autism (1); epilepsy (1); glioma (1); Hypertension (1); keratosis (1); mental disorder (1); metabolic disorder (1); personality disorder (1); pulmonary disorder (1); retinitis pigmentosa (1); schizophrenia (1).